MYH11 (myosin heavy chain 11)
Diseases named in the same sentence as MYH11 in open-access papers (continued):
Sharing a sentence is not in itself a finding about the gene and the disease.
tumor (continued). "However, MYH11 is a possible tumor suppressor, and its involvement in controlling EMT and CRC development is unknown." (PMID 40918458, 2025). "Importantly, functional enrichment analysis revealed that muscle‐related pathways were significantly activated in MYH11+ CAFs, suggesting that MYH11+ CAFs may contributes to the migration and attachment of tumour cells to normal tissue." (PMID 39294858, 2024). "Moreover, we found that MYH11+ CAFs may promote tumour migration via interacting with macrophages, and was associated with poor prognosis in CRC." (PMID 39294858, 2024). "Specifically, these mutations are located on five tumor suppressors (SDHA, RB1CC1, PTCH1, DMBT1, BCR) and eight proto-oncogenes (MERTK, CSF1R, MYB, ROS1, PCM1, FGFR2, MYH11, BRCC3) and have an allele frequency lower than 0.01 in the Genome Aggregation Database (GnomAD)." (PMID 33466296, 2021). "In addition, we also verified four hub genes (CTLA4, CDSN, ACTN2, and MYH11) that their expression levels in tumor tissue might be regulated by the mechanism of DNA methylation." (PMID 35096593, 2021). "Therefore, our findings unveiled the tumor suppressor role of MYH11 in GC." (PMID 34380460, 2021). "Overexpression study results demonstrated that overexpression of MYH11 inhibited the proliferation, invasion, and migration of CRC cells, further supporting its potential as a tumor inhibitor in CRC." (PMID 40918458, 2025). "On the other hand, among the most oxidized proteins in healthy tissue compared to tumor were different isoforms of myosin, including MYH8 and MYH11." (PMID 40461450, 2025). "This subset ultimately acts as a regulator of LCRC aggressiveness, promoting tumor invasion through TGF-β signaling, upregulation of pro-tumor genes (RAMP1, MYLK, MYH11) and activation of muscle-invasive pathways." (PMID 41450739, 2025). "To evaluate the function of MYH11+ CAFs in tumour progression of L‐CRC, we calculated tumour‐related scores in scRNA‐seq of L‐CRC to reveal that MYH11+ CAFs had elevated expression of higher proliferation, stemness and hypoxia scores than other subsets." (PMID 39294858, 2024). "In the tumor tissue of AML patients, the presence of RUNX1::RUNX1T1 and CBFB::MYH11 fusions positively affects the course of the disease." (PMID 38392574, 2024). "In contrast, MYH11+αSMA+ CAFs expressing myosin heavy chain 11 (MYH11) gene, ACTA2, and intermediate levels of CD34 were localized as a single layer encapsulating the tumor nest and orchestrating T-cell exclusion." (PMID 37342322, 2023). "The relative expression levels of MYH11 and CD20 were elevated in stages III/IV compared with stages I/II in both ESCA and STAD samples and were positively correlated with tumour stage (p < 0.05)." (PMID 37189448, 2023). "The two hypomethylated hub genes, CTLA4 and CDSN, were significantly upregulated, and two hypermethylated hub genes, ACTN2 and MYH11, were downregulated in the HNSC tumor samples." (PMID 35096593, 2021). "Some of these switches occur in known tumor drivers, including PPARG, CCND3, RALGDS, MITF, PRDM1, ABI1 and MYH11, for which the switch implies a change in the protein product." (PMID 25578962, 2015). "The results identified two major trajectories: RGS5+ fibroblasts and MYH11+ fibroblasts acted as progenitors, whereas STEAP4+ fibroblasts and Tumor-like fibroblasts represented transitional states, terminally evolving into ECM-remodeling fibroblasts or C7+ fibroblasts." (PMID 40520021, 2025). "Based on these studies, understanding the interaction between MYH11 and ZEB1 and their role in tumor biology may provide insights into new therapeutic targets and prognostic markers." (PMID 40918458, 2025). "A more comprehensive characterization using additional markers such as Pdgfra, Myh11, Pecam, and CD45 could provide deeper insights into the CAF subtypes derived from ASCs within the tumor microenvironment, which should be considered in future investigations." (PMID 39766174, 2024).
tumor (continued). "In the current analysis, we also observed differences between STAD and CRC patients when using MYH11 protein as a prognostic marker, with higher levels of MYH11 in STAD tumours reflecting significantly poorer survival and a relatively better survival rate in CRC tumours." (PMID 37189448, 2023). "Pancreatic stellate co-cultured with PDACs could differentiate both POSTN-positive CAFs (least protumoral) to myosin heavy chain 11 (MYH11) and PDPN-expressed (tumor-supportive) CAFs." (PMID 38234683, 2023). "Furthermore, we found that TNNT1, ACTC1, and MYH11 expression levels were negatively correlated with tumor purity, while TNNI3 expression levels were positively correlated with tumor purity." (PMID 36514150, 2022). "Given MYH11’s established role in smooth muscle contraction and cellular motility, its downregulation in CRC could disrupt tissue architecture, alter stromal signaling, and foster a permissive microenvironment for tumor progression." (PMID 40918458, 2025). "By immunohistochemical detection of MYH11, TNFRSF14, and Ki67 expression in harvested xenograft tumors, we observed a significant increase in MYH11 expression and a significant decrease in Ki67 and TNFRSF14 expression in tumor tissues from the mice injected with cells overexpressing MYH11." (PMID 34380460, 2021). "Likewise, when we explored the effects of IL1β-silenced tumor cells on co-cultured NCFs, we could observe that cocultured fibroblasts lost the expression of inflammatory cytokines, as IL6, LIF or CCL2, while acquired markers of myofibroblasts (ACTA2, PDPN, MYH11, or CNN1)." (PMID 34066976, 2021).
cancer (66 papers, 2007 to 2026). A tumor composed of atypical neoplastic, often pleomorphic cells that invade other tissues. "Further, we identified a potentially novel MYH11+ cancer‐associated fibroblast (CAF) subset predominantly enriched in L‐CRC." (PMID 39294858, 2024). "MYH11 encoding myosin heavy chain 11 has been confirmed its involvement in several types of cancer and is probably related to metabolism-related genes." (PMID 36187094, 2022). "MYH11 has a role in cell migration and interacts with cell adhesion proteins; additionally, mutations in MYH11 have been associated with several cancer types." (PMID 34771455, 2021). "Mutations of the MYH11 gene have been reported in various forms of cancers, including head and neck cancer, non-small-cell lung cancer, bladder cancer, colon adenocarcinoma as well as GC." (PMID 34380460, 2021). "It is likely that MYH11 is expressed in cancer-associated fibroblasts which are especially abundant in diffuse-type GC tissues." (PMID 26016667, 2015). "Furthermore, after mapping the non-synonymous mutations onto the internal branches of the CellPhy tree, we found that all cancer cells harbor somatic variants affecting genes that can contribute to human intestinal neoplasia (i.e., MYH11 and STAG1)." (PMID 35081992, 2022). "MYH11 encodes a protein that participates in muscle contraction through the hydrolysis of adenosine triphosphate; its expression levels are downregulated in several types of cancers." (PMID 33597971, 2021). "The MYH11 gene has a single-nucleotide repeat sequence (C8) in the coding sequence, which may be a mutation target for cancer that exhibits microsatellite instability (MSI)." (PMID 33747044, 2021). "Based on our model, we argue that activating mutations of MYH11 or other human smooth muscle genes could cause invasion of existing cancer in the setting of oxidative stress that is intrinsic to cancers or occurs in the setting of inflammatory conditions that promote cancer formation." (PMID 22973180, 2012). "Despite the significant findings of our study, a substantial gap remains in understanding the intricate mechanisms by which MYH11 exerts its effects in cancer biology." (PMID 40918458, 2025). "CPSCs differentiated into CCL19+ TPSCs in immune‐enriched regions, MYH11+ TPSCs in the stromal region, and PLXDC1+ TPSCs, which exhibited cancer‐associated myofibroblasts (myCAFs) phenotype linked to poor prognosis." (PMID 40091495, 2025). "The upregulated genes were associated with extracellular matrix remodeling and cancer pathways, including LAMC1-3, COL9A2, COL1A1, MYL9, MYH11, and KAT2A." (PMID 39735192, 2024). "Other proteins such as ERα and MYH11 have clear patterns for specific cancers with higher and lower expression of these proteins, with the bimodal distributions more evident that for other proteins." (PMID 39624167, 2024). "Some cancer drivers displayed both decreased accessibility and decreased mRNA levels, e.g., Brca1, E2f7 and Myh11, while others displayed increased accessibility and associated mRNA upregulation, e.g., Msi2, Bace2." (PMID 35269430, 2022). "Beside mesothelial cells, 2 other subtypes of fibroblasts containing myofibroblasts (FB_MYH11) and TGF-β-driven cancer-associated fibroblasts (FB_COMP) were linked to a decreased survival." (PMID 34238352, 2021). "Cluster 0 cells showed fibroblast signatures (RGS5 and NDUFA4L2), cluster 2 cells had strong expression of cancer associated fibroblast (CAF) markers (LUM, SFRP4, and COL1A1), and cluster 5 cells expressed myofibroblast markers (MYH11, TAGLN, and ACTA2)." (PMID 33662621, 2021). "MYH11 expression has been shown to be downregulated in cancers, and its downregulation corresponds to poor prognosis and survival." (PMID 33256002, 2020). "The specific mechanisms of the relationship between the MYH11 gene and myosins in cancer cells requires further investigation." (PMID 27121062, 2016).
cancer (continued). "Additionally, the therapeutic potential of targeting MYH11 in cancer treatment is largely unexplored." (PMID 40918458, 2025). "Truncating mutants of MYH11 may influence the energy balance and motility of cancer cells, since they have been shown to display elevated ATPase and motility activities in cancer." (PMID 40918458, 2025). "There have been some previous studies on the relationship between MYH11 and cancer." (PMID 36596842, 2023). "On this basis, MYH11 mutations may increase cell migration and adhesion by altering MYH1 function (motility and energy dysregulation) in affected cancer cells." (PMID 37598251, 2023). "While the functional role of MYH11 is less studied in cancers." (PMID 34380460, 2021). "This promotes MYH11 as a candidate gene of MSI-related cancers." (PMID 27121062, 2016). "Surprisingly, most of these switches are independent of somatic mutations, except for the tumor suppressor FBLN2 and the oncogene MYH11, suggesting that recurrent isoform switching in cancer is mostly independent of somatic mutations." (PMID 25578962, 2015). "In particular, we predict isoform switches that affect the encoded protein for the cancer drivers CCND3, MYH11, MITF, RALGD5, ABI1, PRDM1 and PPARG, which may have implications for targeted therapy development." (PMID 25578962, 2015). "Moreover, the detailed mechanisms and broader impacts of MYH11 in cancer biology, including its interactions with other signaling molecules and its effects on processes like angiogenesis and immune evasion, remain unclear." (PMID 40918458, 2025). "Given the pivotal role of EMT in cancer progression and the well-established function of ZEB1 as a key EMT regulator, we further explored the potential interplay between ZEB1 and MYH11 in CRC cells." (PMID 40918458, 2025). "As expected, most up-regulated proteins are related to cancer genes, with seven of them known to be enhanced in PCa (SYNM, DES, MYH11, TAGLN, CNN1, LMOD1, and PGM5)." (PMID 38052461, 2024). "The study reported that the potential muscle-specific genes expressed in cancer cells were TNNI1, TNNT1, DES, TRDN, MYH6, MYH11, and MYH13." (PMID 36378654, 2022). "In 2N patients, we saw aberrations, e.g., in Chr.16p13.11, that harbor at least four genes (ABCC1, FOPNL, MYH11, KIAA0430) involved in cancer development or that are present in rare CNVs in cancer patients." (PMID 32577795, 2020). "Genes such as KIF5A, SOX10, MYL9, TRIM9, MYH11, and SNAP25 are known to play important roles in biological development, suggesting that LRP1B may also be a key factor in cancer." (PMID 40170839, 2025). "For immune-related genes, the expression of genes involved in the categories of tight junction such as MYH11, PPP2R2C, and MYL9, cancer development such as TAGLN and CALD1, and acquired immunity such as PCP4 and CXCL13 was upregulated in the LP group when compared with that in the CON group." (PMID 37731924, 2023). "A recent study identified two types of CAF subsets, MYH11+ αSMA+ CAF and FAP+ αSMA+ CAF, which contribute to T-cell exclusion and could restrict T cells contact with cancer cells." (PMID 37173705, 2023). "While expression of ACTA2 – a marker expressed by both myoepithelial cells and cancer-associated fibroblasts (CAFs) – significantly increased in CAS compared to normal stroma, expression of TP63, CHD3, MYH11, SERPINB5 and MME did not increase." (PMID 37391533, 2023). "With respect to the genes having interaction(s) with miRNAs, we realized four down-regulated vDEGs (TMEM100, MYH11, CHRDL1, and FAM107A) to the accompaniment of five up-regulated vDEGs (KLK10, CLDN1, SLC6A6, MMP11, and SLC7A5) being documented by the GEPIA in both COAD and READ cancer types." (PMID 35333898, 2022). "Among Cancer Gene Census genes, 1346 events were detected in 947 different loci, with the most recurrent ones being those in CLTCL1 (24 cases), CSMD3 (21 cases), MYH9 (20 cases), ANK1 (19 cases), TPR (19 cases), MYH11 (18 cases), PTPN13 (18 cases), and POLQ (17 cases)." (PMID 33809641, 2021).
cardiovascular diseases (5 papers, 2016 to 2025). "Additional testing in mouse models will help determine the role of other common MYH11 variants in sporadic cardiovascular disease." (PMID 26893369, 2016). "Going forward, it will be interesting to determine whether germline MYH11 variants that are strongly linked to cardiovascular disease affect myosin regulation." (PMID 26893369, 2016). "In summary, the potentially novel Myh11-CreNLSP2A and Myh11-CreERT2–P2A mouse models provide powerful research tools for investigating SMC biology and related cardiovascular disorders." (PMID 37289544, 2023). "However, the function of MYH11 c.5081A>G in cardiovascular diseases remains unclear." (PMID 36440024, 2022). "Therefore, we believe that MYH11 c.5081A>G may be essential in developing cardiovascular diseases." (PMID 36440024, 2022). "In cardiovascular diseases, defects in the function of actin or myosin (ACTA2 or MYH11) result in diminished actin–myosin interactions and lead to diseases." (PMID 34858981, 2021). "Genomic test identified variants of uncertain significance in the TTN, MYH11, and RAF1 genes, which are associated with cardiovascular diseases but not directly linked to AF." (PMID 40625395, 2025). "Combined with recently generated BAC transgenic Myh11-CreERT2-RAD mice and the Itga8-CreERT2 mouse models, our models will help expand the research toolbox, facilitating unbiased and comprehensive research in SMCs and SMC-dependent cardiovascular diseases." (PMID 37289544, 2023). "In comparison, no mutations in MYH11 and ACTA2 were detected in her father who had no cardiovascular diseases." (PMID 36440024, 2022).
infection (5 papers, 2020 to 2025). The state of being infected such as from the introduction of a foreign agent such as serum, vaccine, antigenic substance or organism. "Myh11 upregulation may be associated with blood vessel permeability due to peripheral cell infiltration to the CNS to fight the infection." (PMID 40038673, 2025). "Infection induced gland hyperplasia, which was accompanied by an expansion of surrounding Myh11+ cells." (PMID 35332152, 2022). "Two days pre-intravitreal injection, Myh11-derived MSCs (derived from Myh11-tdTomato mice) were infected at 3000 MOI of Smad4-shRNA or scramble-shRNA adenovirus vectors, with co-expression of GFP indicating successful infection." (PMID 32978500, 2020).
connective tissue diseases (2 papers, 2024 to 2025). "MYH11 has been associated with vascular and connective tissue disorders." (PMID 39480826, 2024). "We propose that MYH11 and SYNPO2 are novel genes in EMILIN1-related Connective Tissue Disease with both contributing to presentations common to this disorder and Lethal Arteriopathy Syndrome due to Fibulin-4 Deficiency." (PMID 39480826, 2024). "However, in contrast to these connective tissue diseases, Myh11ΔK/ΔK mice and patients with FTAAD caused by MYH11 pathogenic variants do not show syndromic features." (PMID 40869178, 2025).
vascular disorder (2 papers, 2016 to 2024). A general term used to describe any disease affecting blood vessels]. "MYH11 was the first gene defect reported in the gene family of smooth muscle contraction-associated vasculopathy." (PMID 38773466, 2024). "Collectively, these findings argue that MYH11 coding variants could be risk factors for intestinal and vascular disorders in humans, and that their pathogenesis might be linked to periodic redox stress." (PMID 26893369, 2016).
retinopathy (1 paper, 2020). "We demonstrate retinal fibrosis within a murine model of oxygen-induced retinopathy resulting from the intravitreal injection of adipose Myh11-derived mesenchymal stem cells, with ensuing myofibroblast differentiation." (PMID 32978500, 2020). "Therefore, we sought to rigorously explore the cell fate of intravitreally injected Myh11-derived MSCs in a retinopathy model, specifically the oxygen-induced retinopathy (OIR) model, and access the impact of MSCs on retinal angiogenesis and potential fibrosis." (PMID 32978500, 2020). "Since TGFβ1 levels were not significantly upregulated in the oxygen-induced retinopathy murine retinal environment in which Myh11-derived MSCs were injected, we can only speculate as to the other factors contributing to this myofibroblast differentiation in the eye." (PMID 32978500, 2020).
MYH11 also shares sentences with these, for which no sentence is quoted: thoracic aortic aneurysm and dissection (7 papers); acute lymphoblastic leukemia (5); bladder cancer (4); invasive carcinoma (4); Myelodysplasia (4); atrial fibrillation (3); breast (3); cerebrovascular disease (3); hyperlipidemia (3); Loeys-Dietz syndrome (3); lymphoid neoplasm (3); megacystis-microcolon-intestinal hypoperistalsis syndrome (3); myelodysplastic syndrome (3); myeloid leukemia (3); myeloid neoplasm (3); abdominal aortic aneurysm (2); Acute myelomonocytic leukemia (2); cardiac disease (2); cholestasis (2); chronic myelocytic leukemia (2); dilated cardiomyopathy (2); in situ carcinoma (2); ischemic stroke (2); lung adenocarcinoma (2); myelofibrosis (2); myeloid sarcoma (2); myocardial infarction (2); pancreatic cancer (2); stomach cancer (2); Vascular Ehlers-Danlos Syndrome (2).
A further 93 diseases each share a sentence with MYH11 in 2 papers or fewer.